RFX3 (regulatory factor X3)
Description:
Transcription factor required for ciliogenesis and islet cell differentiation during endocrine pancreas development. Essential for the differentiation of nodal monocilia and left-right asymmetry specification during embryogenesis. Required for the biogenesis of motile cilia by governing growth and beating efficiency of motile cells. Also required for ciliated ependymal cell differentiation. Regulates the expression of genes involved in ciliary assembly (DYNC2LI1, FOXJ1 and BBS4) and genes involved in ciliary motility (DNAH11, DNAH9 and DNAH5) (By similarity). Together with RFX6, participates in the differentiation of 4 of the 5 islet cell types during endocrine pancreas development, with the exception of pancreatic PP (polypeptide-producing) cells. Regulates transcription by forming a heterodimer with another RFX protein and binding to the X-box in the promoter of target genes. Represses transcription of MAP1A in non-neuronal cells but not in neuronal cells.
Tractability: Antibody: its Gene Ontology location is reachable by antibodies, with medium confidence. PROTAC: ubiquitination databases record sites on it; its protein half-life has been measured.
Gene: Protein-coding gene on chromosome 9 (3,218,297 to 3,526,022, reverse strand). Ensembl gene ENSG00000080298.
Subcellular location: Nucleus
Subcellular location (Human Protein Atlas): Nucleoplasm; Cytosol; Golgi apparatus; Vesicles
Gene Ontology:
Molecular function: protein binding; sequence-specific double-stranded DNA binding; transcription cis-regulatory region binding; DNA binding; DNA-binding transcription factor activity; DNA-binding transcription factor activity, RNA polymerase II-specific; RNA polymerase II cis-regulatory region sequence-specific DNA binding; sequence-specific DNA binding
Biological process: negative regulation of DNA-templated transcription; positive regulation of DNA-templated transcription; cell maturation; cilium assembly; cilium-dependent cell motility; endocrine pancreas development; epithelial cilium movement involved in determination of left/right asymmetry; positive regulation of transcription by RNA polymerase II; positive regulation of type B pancreatic cell development; regulation of DNA-templated transcription; regulation of insulin secretion; regulation of transcription by RNA polymerase II; DNA-templated transcription; type B pancreatic cell maturation
Cellular component: chromatin; nucleoplasm; nucleus; transcription regulator complex; extracellular region
Genetic constraint (gnomAD): Loss-of-function variants: 9 observed, 74.13 expected, observed/expected ratio (o/e) 0.12, 90% interval 0.072 to 0.21. The upper end of that interval is the gene's LOEUF score, 0.21, which puts it in group 1 of 6, group 1 being the genes least tolerant of losing a copy. Missense variants: 520 observed, 760.36 expected, observed/expected ratio (o/e) 0.68, 90% interval 0.64 to 0.74. Synonymous variants: 294 observed, 274.11 expected, observed/expected ratio (o/e) 1.07, 90% interval 0.97 to 1.18.
Gene-disease validity (ClinGen):
ClinGen rates the evidence that RFX3 causes each of these diseases.
complex neurodevelopmental disorder (autosomal dominant): Definitive. A disorder that involves more than one phenotype associated with the central nervous system, including but not limited to intellectual disability, autism, and seizures (epilepsy).
Homologues: Orthologues: macaque RFX3 (99% identical), dog RFX3 (99% identical), pig RFX3 (99% identical), rabbit RFX3 (99% identical), rat Rfx3 (99% identical), mouse Rfx3 (99% identical), chimpanzee RFX3 (98% identical), guinea pig RFX3 (94% identical), tropical clawed frog rfx3 (93% identical), zebrafish rfx3 (76% identical), Drosophila melanogaster Rfx (43% identical). Paralogues in human: RFX2 (64% identical), RFX1 (57% identical), RFX6 (26% identical), RFX4 (25% identical), RFX7 (19% identical), RFX8 (12% identical), RFX5 (11% identical).
Diseases named in the same sentence as RFX3 in open-access papers:
RFX3 is named in the same sentence as 40 diseases in open-access papers, as found by Europe PMC text mining. Sharing a sentence is not in itself a finding about the gene and the disease. The quoted sentences say what the papers report.
Hydrocephalus (8 papers, 2007 to 2023). Hydrocephalus is an active distension of the ventricular system of the brain resulting from inadequate passage of CSF from its point of production within the cerebral ventricles to its point of absorption into the systemic circulation. "The ablation of Rfx3 in mice causes defective ciliogenesis in node and ependymal cells, resulting in left–right asymmetry defects and hydrocephalus, respectively." (PMID 35087169, 2022). "Rfx3 deficient mouse mutants exhibit several hallmarks of ciliopathies and in particular left-right asymmetry defects and hydrocephalus." (PMID 22479201, 2012). "Aberrations in Rfx3 and Rfx4 have been linked to hydrocephalus in mice." (PMID 29298325, 2018). "RFX3-deficiency leads to aberrant ciliation and hydrocephalus in mice." (PMID 24229449, 2013). "However, hydrocephalus can also occur independently of aqueduct stenosis as seen in RFX3-deficient mice." (PMID 24229449, 2013). "Indeed, Rfx3 controls the growth of mouse embryonic node cilia and Rfx3 loss-of-function leads to hydrocephalus with differentiation defects of ciliated ependymal cells of the choroid plexus and subcommisural organ." (PMID 17875208, 2007). "Rfx3 KO mice exhibited abnormal cilia development in the nodal cilium, truncated cilia on immature β-cells of the pancreas, and hydrocephalus." (PMID 29298325, 2018). "Rfx3−/− mice show several hallmarks of ciliopathies, including left-right asymmetry defects, hydrocephalus, and corpus callosum agenesis; the phenotype of heterozygous mice was not reported." (PMID 25844147, 2015). "Another example of a novel prediction is RFX3 for somatotropin – this gene has no direct co-occurrence with hormone-related terms, but is known to play a role in hydrocephalus disease, which is associated with deficiency in this growth hormone." (PMID 37093889, 2023). "Regulatory Factor X3 (RFX3) is a transcription factor involved in the control of ciliogenesis, and Rfx3–deficient mice show several hallmarks of ciliopathies including left–right asymmetry defects and hydrocephalus." (PMID 22479201, 2012). "It has been demonstrated that knockout of RFX3 in mice caused hydrocephalus but not stenosis of the Sylvius aqueduct, which is characterized by hypoplasia of secretory ependymal cells of the subcommissural organ and changes in the number rather than ultrastructure of cilia." (PMID 37008045, 2023).
ciliopathies (6 papers, 2008 to 2022). "Rfx3 mouse mutants thus appear to be particularly informative for understanding the molecular mechanisms that govern early midline patterning and offers a rare insight into the causes of CC defects in ciliopathies." (PMID 22479201, 2012). "Hence, the RFX3 mutant mouse model brings novel understandings of the mechanisms that underlie CC agenesis in ciliopathies." (PMID 22479201, 2012). "RFX3 may regulate the transcription of many genes that, when mutated, cause cilia defects and many disease conditions collectively called ciliopathies." (PMID 18673564, 2008). "In the Olig2-KO mouse or Rfx3-KO (ciliopathy) mouse diencephalon, it was described as a prethalamic malformation, followed by disorganized extension of TCAs." (PMID 35221935, 2022). "Deregulation of fatty acid metabolism may affect fatty acylation of RFX3 and thereby the RFX3-mediated protein interaction network, leading to ciliopathies and metabolic disorders such as diabetes." (PMID 31252577, 2019). "Hence Rfx2-/- mice do not exhibit the ciliopathy hallmarks observed in Rfx3-/- mice or other phenotypes observed for Rfx-deficient mice." (PMID 26162102, 2015).
gout (5 papers, 2017 to 2018). A condition characterized by painful swelling of the joints, which is caused by deposition of urate crystals. "A recent genome-wide association study (GWAS) of gout identified three new loci for gout in Han Chinese: regulatory factor X3 (RFX3), potassium voltage-gated channel subfamily Q member 1 (KCNQ1), and breast carcinoma amplified sequence 3 (BCAS3)." (PMID 29879923, 2018). "Rs12236871 of RFX3 gene was associated with gout in a Han Chinese male cohort." (PMID 30123371, 2018). "We genotyped the variants of RFX3 (rs12236871), KCNQ1 (rs179785) and BCAS3 (rs11653176) in 723 Japanese clinically defined gout cases and 913 controls by TaqMan method." (PMID 29879923, 2018). "The Chinese GWAS used hyperuricaemic controls in follow-up testing to demonstrate that the newly discovered loci (BCAS3, RFX3 and KCNQ1) are likely to be involved in pathways leading to presentation with gout in people with hyperuricaemia." (PMID 28566086, 2017).
diabetes (4 papers, 2008 to 2025). "These insights into RFX3 function have implications for understanding islet biology and potential diabetes susceptibility." (PMID 40263183, 2025). "RFX3-deficient mice show left-right (L-R) asymmetry defects, developmental defect, diabetes, and congenital hydrocephalus in mice." (PMID 18673564, 2008). "For example, RFX3-deficient mice show left-right (L-R) asymmetry defects, developmental defects, diabetes, and congenital hydrocephalus." (PMID 18673564, 2008). "While another regulatory factor X family member, RFX6, is known to regulate human islet development and mutations cause monogenic diabetes, the role of RFX3 in human development remains unclear." (PMID 40263183, 2025). "While RFX6 mutations are linked to neonatal diabetes and type 2 diabetes, the role of RFX3 in diabetes is less understood." (PMID 40263183, 2025). "Instead, RFX3 loss increased TXNIP, a pro-apoptotic protein linked to diabetes and oxidative stress-induced beta cell death." (PMID 40263183, 2025). "The relationship between RFX3 and genes involved in monogenic diabetes has been established." (PMID 40263183, 2025).
congenital hydrocephalus (3 papers, 2008 to 2017). Hydrocephalus that is present at birth. "Finally, we examined RFX3, required for the differentiation of ependymal cells that contribute to CSF homeostasis, and who’s absence causes congenital hydrocephalus in mice." (PMID 29170629, 2017). "Here, loss of RFX3 causes aberrant ciliation in the SCO and a decrease in RF immunoreactivity, leading to congenital hydrocephalus without collapse of the aqueduct." (PMID 24229449, 2013).
endometrial cancer (2 papers, 2019 to 2022). Primary or metastatic malignant neoplasm involving the endometrium (mucous membrane that lines the endometrial cavity). "Regulatory factor X3 (RFX3) is associated with predisposition genes in endometrial cancer, metastasis in BC, chromosomal rearrangement in B lymphocytes, and the promotion of cancer cell proliferation." (PMID 36072666, 2022). "Seven genes, including RBM12, NDUFB6, ATP6V1A, RECK, SLC35E1, RFX3 (Bonferroni-corrected P < 0.05) and ATP8A1 (suggestive P < 10−5), and one long non-coding RNA, DLGAP4-AS1 (Bonferroni-corrected P < 0.05), were associated with endometrial cancer." (PMID 31338326, 2019).
Insulin resistance (2 papers, 2014 to 2016). Increased resistance towards insulin, that is, diminished effectiveness of insulin in reducing blood glucose levels. "In addition, by activating binding of RFX3, an interesting transcription factor to act on glucokinase gene, we may hypothesis ZCWPW1 decreases risk of LOAD through suppressing insulin resistance." (PMID 26958812, 2016). "Given the proposed link between insulin resistance and AD as a result of insulin degrading enzyme (IDE), RFX3 may be an interesting transcription factor to examine in the context of LOAD pathogenesis." (PMID 24743338, 2014).
schizophrenia (2 papers, 2015 to 2021). A major psychotic disorder characterized by abnormalities in the perception or expression of reality. "A deletion of RFX3 has also been reported in a patient affected by schizophrenia." (PMID 34768579, 2021). "A 440 kb deletion including RFX3 was observed in one individual in a schizophrenia cohort." (PMID 25844147, 2015).
attention deficit-hyperactivity disorder (1 paper, 2025). A disorder characterized by a marked pattern of inattention and/or hyperactivity-impulsivity that is inconsistent with developmental level and clearly interferes with functioning in at least two settings (e.g. at home and at school). "These include regions with nearest protein-coding genes such as BCAS3, RFX3, SOBP, and PEX14, mutations in which have been linked to intellectual disability, neurological deficits, attention deficit hyperactivity disorder, or autism spectrum disorders." (PMID 41279093, 2025).
breast carcinoma (1 paper, 2017). "We demonstrate that SPEN positively regulates primary cilia formation and cell migration in breast cancer, possibly via the transcriptional regulation of RFX3, a ciliogenic transcription factor." (PMID 28877752, 2017). "We also found that SPEN knockdown in Hs578T cells decreased RFX3 levels, suggesting that SPEN may positively regulate RFX3 expression in different breast cancer cells." (PMID 28877752, 2017).
COVID-19 (1 paper, 2023). A disease caused by infection with severe acute respiratory syndrome coronavirus 2. "For example, RFX2 and RFX3 were activated in ciliated cells under all three conditions, but the majority of targets were downregulated in mild/moderate COVID-19 patients compared to healthy cells." (PMID 37936693, 2023). "Regulators RFX2 and RFX3 were shared between healthy individuals and COVID-19 patients, but the two regulators showed different target genes or target expression levels in the two sample types." (PMID 37936693, 2023). "Furthermore, RFX3 upregulated most of its target genes in patients with severe COVID-19." (PMID 37936693, 2023). "For example, RFX2 and RFX3 showed high activity in ciliated cells regardless of disease severity, while XBP1, NR2F6, SPDEF, and ELF3 were preferentially activated in goblet cells in patients with severe COVID-19, and KLF5 and STAT2 were coactivated in patients with mild/moderate COVID-19." (PMID 37936693, 2023).
dyslexia (1 paper, 2014). A learning disorder characterized by an impairment in processing written words. "Four out of the five most strongly associated genes in the GSEA of the GWAS study for relative hand skill in the dyslexia cohort are involved in ciliogenesis: meiosis-specific nuclear structural protein 1 (MNS1), regulatory factor X 3 (RFX3), GLI family zinc finger 3 (GLI3), as well as PKD2." (PMID 24275328, 2014).
glioblastoma (1 paper, 2022). The most malignant astrocytic tumor (WHO grade IV). "In addition, RFX2 is reported to be involved in the regulation of the promoter of fibroblast growth factor-1B, a major transcript within the human brain and retina, by forming a complex with RFX3 in human glioblastoma cells, suggesting that RFX2 alone is insufficient for its regulation." (PMID 35714115, 2022).
heart malformations (1 paper, 2020). "RFX3 is a highly constrained ciliogenic transcription factor that leads to pronounced laterality defects, and disruption of RFX3 leads to congenital heart malformations in mice (MGI: 5560494)." (PMID 32349777, 2020).
Hypoglycemia (1 paper, 2023). A decreased concentration of glucose in the blood. "SMARCA2 and RFX3 were proposed as potential candidates for the hypoglycemia, but no experimental evidence has been provided." (PMID 37065762, 2023).
lupus (1 paper, 2017). "In addition, in a mouse model that simulates lupus progression, animals experienced an increased expression of MAP17 connected with a decrease in RFX3, a negative regulator of HLAs, and decreases in HERC2 and ADNP." (PMID 29228712, 2017).
Meckel Gruber Syndromes (1 paper, 2021). "Rfx3 encodes a transcription factor controlling the expression of many genes involved in ciliary assembly and function; RPGRIP1L is mutated in Joubert and Meckel Gruber Syndromes and codes for a transition zone protein." (PMID 33604340, 2021).
type 2 diabetes (1 paper, 2025). "Deletion of this complex reduces RFX3 expression, underscoring its importance in islet function and type 2 diabetes susceptibility." (PMID 40263183, 2025).
ventricular septal defect (1 paper, 2023). The presence of a defect (opening) in the septum that separates the two ventricles of the heart. "Among these phenotypes, ventricular septal defect is notable in that it is matched directly to RFX3 located at 9p24.2." (PMID 36691971, 2023).
infection (6 papers, 2018 to 2025). The state of being infected such as from the introduction of a foreign agent such as serum, vaccine, antigenic substance or organism. "Also, the ciliogenesis regulator RFX3 remained repressed in ciliated cells at 12 months post infection (Dataset EV6)." (PMID 40119174, 2025). "The late decrease in transcripts encoding ciliogenesis regulators (FOXJ1, RFX3) and ciliary components (DNAH7) may in part result from the death of ciliated cells detectable at a more advanced stage of infection." (PMID 34272374, 2021). "Following infection of the bronchial epithelium with SARS-CoV-2, a reduction in the expression of cilia regulatory factors, including FOXJ1, RFX3, and DNAH7, was observed." (PMID 39195243, 2024). "At 3 days post-infection (DPI 3), we confirmed the successful overexpression of RFX2, RFX3, RFX4, and RFX5 in stem cells." (PMID 38386071, 2024).
cancer (4 papers, 2014 to 2023). A tumor composed of atypical neoplastic, often pleomorphic cells that invade other tissues. "BTBD10 (43%), PLCD3 (27%), and RFX3 (24%) were frequently mutated in pan-cancer." (PMID 37007130, 2023). "Three variants in RBM12, one variant in NDUFB6, ten variants in DLGAP4-AS1, five variants in ATPV1A, eleven variants in RECK, four variants in SLC35E1, eight variants in RFX3, and eight variants in ATP8A1 were known somatically acquired mutations in various cancers." (PMID 31338326, 2019). "Two cancers (#615 and #3008) had acquired homozygous deletions at the CDKN2A locus (chr9p21.3), and other homozygous deletions present in single cancers involved genes such as PPARGC1A, RFX3 and FAT1." (PMID 24777035, 2014).
tumor (4 papers, 2018 to 2022). "Finally, we were also able to identify a number of TFs of interest, including RFX3 and RFX7 from snATAC-seq analysis of the recurrent tumor autopsy specimen." (PMID 35941215, 2022). "While RFX3 was differentially expressed across the tumor-cell populations, RFX7 was not and would have been missed using snRNA-seq analysis alone, further highlighting the value of multi-omic data analysis in identifying potential TF targets." (PMID 35941215, 2022).
neurodevelopmental disorder (1 paper, 2024). A behavioral and cognitive disorder with onset during the developmental period that involves impaired or aberrant development of intellectual, motor, or social functions. "MYT1L and RFX3 were also ranked as strong candidates specifically for ASD, rather than other neurodevelopmental disorders, according to the EAGLE score." (PMID 38409172, 2024).
RFX3 also shares sentences with these, for which no sentence is quoted: asthenozoospermia (1 paper); Ataxia (1); atherosclerosis (1); autoimmune disease (1); ependymoma (1); epilepsy (1); glioma (1); hyperuricaemia (1); Intellectual disability (1); MERRF) syndrome (1); metabolic disorders (1); myoclonus epilepsy (1); myoclonus epilepsy associated with ragged-red fibres (1); psychiatric disorder (1); retinopathy (1); type 1 diabetes mellitus (1); Wilms tumor (1).